C4orf17 (chromosome 4 open reading frame 17)
Synonyms: DKFZP434G072
Tractability: No criterion of Open Targets' tractability assessment is met for any kind of drug.
Gene: Protein-coding gene on chromosome 4 (99,511,012 to 99,542,303, forward strand). Ensembl gene ENSG00000138813.
Subcellular location (Human Protein Atlas): Mid piece
Gene Ontology:
Molecular function: protein binding
Genetic constraint (gnomAD): Loss-of-function variants: 18 observed, 23.6 expected, observed/expected ratio (o/e) 0.76, 90% interval 0.53 to 1.13. The upper end of that interval is the gene's LOEUF score, 1.13, which puts it in group 4 of 6, group 1 being the genes least tolerant of losing a copy. Missense variants: 369 observed, 388.1 expected, observed/expected ratio (o/e) 0.95, 90% interval 0.87 to 1.04. Synonymous variants: 129 observed, 136.35 expected, observed/expected ratio (o/e) 0.95, 90% interval 0.82 to 1.1.
Homologues: Orthologues: chimpanzee C4H4orf17 (99% identical), macaque C5H4orf17 (93% identical), pig C4orf17 (75% identical), dog C4orf17 (74% identical), rabbit C4orf17 (71% identical), rat C2h4orf17 (55% identical), mouse 4930579F01Rik (53% identical), guinea pig CUNH4orf17 (46% identical).
Diseases named in the same sentence as C4orf17 in open-access papers:
C4orf17 is named in the same sentence as 6 diseases in open-access papers, as found by Europe PMC text mining. Sharing a sentence is not in itself a finding about the gene and the disease. The quoted sentences say what the papers report.
alcoholic fatty liver disease (1 paper, 2022). Lipid infiltration of the hepatic parenchymal cells that is due to alcohol abuse. "As the near downstream gene of C4orf17, MTTP has been suggested to be related to alcoholic fatty liver disease, possibly because alcohol exposure could increase triglyceride and cholesterol levels." (PMID 35864541, 2022).
colorectal cancer (1 paper, 2014). A primary or metastatic malignant neoplasm that affects the colon or rectum. "To do this, we selected a small sub-group of these genes that remained transcriptionally silenced in the colorectal cancer cell lines HCT116 and SW480 (ARRDC5, C4orf17, C20orf201, DDX4, NT5C1B, STRA8, TDRD12)." (PMID 25594001, 2014).
cancer (2 papers, 2019 to 2024). A tumor composed of atypical neoplastic, often pleomorphic cells that invade other tissues. "By far, little is known about the relevance of C4orf17 (harboring cg26647453) and UNKL (harboring cg26728422) in cancers." (PMID 37830163, 2024).
C4orf17 also shares sentences with these, for which no sentence is quoted: glioma (1 paper); ovarian carcinoma (1); tumor (1).